MIR326 (microRNA 326)
Synonyms: hsa-mir-326; MIRN326; mir-326
Gene: MicroRNA gene on chromosome 11 (75,335,092 to 75,335,186, reverse strand). Ensembl gene ENSG00000199090.
Gene Ontology:
Biological process: miRNA-mediated post-transcriptional gene silencing
Cellular component: RISC complex
Homologues: Orthologues: chimpanzee ptr-mir-326 (100% identical), guinea pig MIR326 (94% identical), mouse Mir326 (94% identical), dog MIR326 (93% identical), pig ssc-mir-326 (93% identical), rat Mir326 (93% identical), macaque MIR326 (64% identical), rabbit MIR326 (60% identical).